CDK4 (cyclin dependent kinase 4)
Diseases named in the same sentence as CDK4 in open-access papers (continued):
Sharing a sentence is not in itself a finding about the gene and the disease.
interstitial lung disease (14 papers, 2020 to 2025). A diverse group of lung diseases that affect the lung parenchyma. "In our cohort, among the patients that had interstitial lung disease (ILD) associated with CDK4/6 inhibitors, 60% of patients had lung metastases, 50% had a history of chest radiation, and 20% had known pulmonary comorbidities." (PMID 40142360, 2025). "Interstitial lung disease (ILD) associated with CDK4/6 inhibitors is a rare (1–3.3%) but profound adverse effect." (PMID 40142360, 2025). "All CDK4/6 inhibitors were associated with myelosuppression, gastrointestinal toxicity, interstitial lung disease (ILD), and QT prolongation." (PMID 41458615, 2025). "Despite the high therapeutic efficacy of CDK4/6 inhibitors, they are associated with various adverse effects, including potentially fatal interstitial lung disease." (PMID 39000513, 2024). "CDK4/6i significantly increased the risk of interstitial lung disease/pneumonitis, with an overall incidence of 1.6%." (PMID 36765648, 2023). "Here, we evaluated the incidence of interstitial lung disease associated with CDK4/6 inhibitor use in clinical practice." (PMID 33939324, 2022). "The aim of this study was to evaluate the clinical incidence of interstitial lung disease caused by two CDK4/6 inhibitors, abemaciclib and palbociclib, and assess the relationship between each drug and interstitial lung disease." (PMID 33939324, 2022). "Several anti-HER2 therapies, as well as other anticancer agents (e.g., cyclin-dependent kinase-4/-6 inhibitors, immune checkpoint inhibitors, mammalian target of rapamycin [mTOR] inhibitors), have been linked to an increased risk of drug-induced interstitial lung disease (ILD)." (PMID 32591987, 2020). "We further analyzed the venous thromboembolism events (TE), interstitial lung disease (ILD), and QT prolongation associated with CDK4/6 inhibitors." (PMID 41458615, 2025). "These cases highlight a potential interaction between CDK4/6 inhibitors and thoracic radiotherapy, resulting in interstitial lung disease." (PMID 41244784, 2025). "The Japanese Ministry of Health, Labour and Welfare has issued a warning about interstitial lung diseases as an adverse effect of CDK4/6 inhibitors." (PMID 33939324, 2022). "Interstitial lung disease has been listed as a serious adverse effect in the package inserts of the CDK4/6 inhibitors abemaciclib and palbociclib." (PMID 33939324, 2022). "However, there are currently insufficient data and evidence to apply a similar strategy to cases of CDK4/6 inhibitor-induced interstitial lung disease (ILD)." (PMID 40142360, 2025). "Additionally, extensive laboratory research is required to further explore the specific molecular mechanisms by which radiotherapy combined with CDK4/6is induces interstitial lung disease, thereby enabling early prevention and precise diagnosis and treatment." (PMID 41244784, 2025). "A study that assessed the pulmonary toxicity of CDK4/6i by analyzing the publicly available FDA Adverse Event Reporting System demonstrated that interstitial lung disease represented 2.1% of total reports recorded for ABM but only 0.3% of total reports recorded for PAL and RIB36." (PMID 38684839, 2024). "We believe that these results may be useful in preventing the occurrence of interstitial lung disease when using CDK4/6 inhibitors." (PMID 33939324, 2022). "Research on the interaction of CDK4/6i and radiotherapy are scarce, but we observed some unexpected and severe toxicity, such as interstitial lung disease (ILD)." (PMID 41244784, 2025). "Information on new agents, such as CDK4/6 inhibitors, is useful for maintaining patient quality of life in cases of adverse events, especially interstitial lung disease, wherein the mechanism of event onset is typically unknown, and no preventive or therapeutic measures have been established." (PMID 33939324, 2022).
interstitial lung disease (continued). "CDK4/6i and ICB monotherapy are shown to have overlapping toxicities, particularly hepatic events and interstitial lung disease/pneumonitis, and adverse events were found to be a leading cause of treatment discontinuation." (PMID 38409585, 2024).
oral squamous cell carcinoma (14 papers, 2011 to 2025). "Moreover, a previously reported study has demonstrated a positive correlation between PTHLH and cyclin-dependent kinase 4 (CDK4) in oral squamous cell carcinoma cells, which is vital for the substantial replicative potential of human chondrocytes in vitro." (PMID 33177241, 2020). "Similarly, it was reported that Yap1 formed complex with TEAD4 in the nuclei regulating the transcriptions of G1 arrest-related genes, such as CCND1, CCNE, CDK2, CDK4, and CDK6, in human oral squamous cell carcinomas." (PMID 31455378, 2019). "The treatment of oral squamous cell carcinoma cells, Cal27, GNM, and WSU-HN6, with a H2S donor, NaHS, significantly downregulated cell cycle regulatory genes, RPA70 and RB1, and upregulated proliferating cell nuclear antigen and cyclin-dependent kinase 4 (CDK4), resulting in cell proliferation." (PMID 29018341, 2017).
acute myeloid leukemia (13 papers, 2016 to 2024). Acute myeloid leukemia (AML) is a group of neoplasms arising from precursor cells committed to the myeloid cell-line differentiation. "FLX925 selectively acts on FLT3 and CDK4/6, and its current indication is acute myeloid leukemia (AML)." (PMID 38138549, 2023). "The activity of the CDK4/CDK6/Cyclin D complex is increased in acute myeloid leukemia." (PMID 27323399, 2016). "Recent studies demonstrated high potency of combining novel Erk1/2i (LY3214996) and CDK4/6i (LY2835219) in solid tumors and acute myeloid leukemia, and clinical trials evaluating Erk1/2i + CDK4/6i therapy are ongoing in advanced cancers." (PMID 35082402, 2022). "This dependency results in a high vulnerability toward inhibitors of CDK4 and CDK6 and suggests new avenues for therapeutic intervention against acute myeloid leukemia." (PMID 33217477, 2021). "Additionally, in acute myeloid leukemia (AML), tumor cell supernatant represses the cell cycle entry of activated T cells by inhibiting the phosphorylation of CDK4/6 sites on pRb." (PMID 33396222, 2020).
mucosal melanoma (13 papers, 2011 to 2025). A melanoma that arises from a mucosal site. "For example, in mucosal melanoma, there is a frequent occurrence of CDK4 protein expression in combination with TERT (telomerase reverse transcriptase) amplification." (PMID 39598629, 2024). "In a mouse model (patient derived xenograft) of human mucosal melanoma carrying CDK4 amplification, a robust anti-tumor effect of palbociclib has been reported." (PMID 34485433, 2021). "To date, the use of CDK4/6 inhibitors in patients with mucosal melanoma harboring amplification of CDK4 is under evaluation in clinical trials." (PMID 35008570, 2021). "The dysregulation of cell cycle progression, caused by CDK4 amplification and/or CCND1 amplification and/or p16 (CDKN2A) loss, is a key genetic feature in mucosal melanoma." (PMID 35008570, 2021). "The molecular mechanisms of CDK4/6 inhibitors on the proliferation of mucosal melanoma were analyzed by RNAseq." (PMID 31358010, 2019). "CDK4 signaling variations predict the effectiveness of CDK4 inhibitors in mucosal melanoma." (PMID 31358010, 2019). "CDK4 amplification is relatively common in acral and mucosal melanomas." (PMID 21479172, 2011). "Hence, alterations in CDK4 signaling components may predict response to CDK4 inhibitors in patients with mucosal melanoma." (PMID 34149718, 2021). "The combined inhibition of CDK4, MDM2 and TERT presents a promising therapeutic strategy for mucosal melanoma, as amplifications of these three genes frequently co-occur in this cancer subtype." (PMID 39598629, 2024). "At present, some studies have found that mutations that activate SF3B1 and KIT, the deletion of CDKN2A, PTEN, or SPRED1, and the amplification of CDK4, TERT, KIT, MDM2, or CCND1 are common in mucosal melanoma." (PMID 38065883, 2023). "All but one of the eight tumors in this study with translocations between 5p and 12p, usually resulting in amplifications of MDM2/CDK4 and TERT, were oral mucosal melanomas and of East Asian ancestry." (PMID 31320640, 2019).
retinoblastoma (13 papers, 2015 to 2025). A malignant tumor that originates in the nuclear layer of the retina. "More importantly, 4 DNA-based subtypes, and a ctDNA-based genomic signature tracking retinoblastoma loss-of-heterozygosity, are significantly associated with poor response and survival outcome following ET + CDK4/6i, independently of plasma tumor fraction." (PMID 36859416, 2023). "These concepts have unveiled a new therapeutic potential for CDK4/6 inhibitors as myeloid-protective agents in retinoblastoma (RB)-deficient cancers, with trilaciclib emerging as the pioneer in this class." (PMID 40478388, 2025). "Specifically, p27 inhibits CDK2 and CDK4/6 thereby preventing the phosphorylation of the Retinoblastoma." (PMID 41009443, 2025). "On the other hand, irradiation significantly increased the level of Cyclin D1, a cell cycle promoter that regulates cell cycle progression by phosphorylating CDK4/6 to inhibit retinoblastoma." (PMID 36092734, 2022). "The mechanism of actions for CDK4/6 inhibitors is centered on RB1, the product of the retinoblastoma tumor susceptibility gene RB1." (PMID 35740538, 2022). "The implications of these results are that targeting the Cdk4/6 - E2f signalling pathway may be a relevant and complementary regime for retinoblastoma with MYCNAs." (PMID 37606819, 2024). "However, CDK4/6 inhibitors might be not efficacious for those with a retinoblastoma-deficient tumor." (PMID 38017560, 2023). "Alteration of the cyclin-dependent kinase 4–6 (CDK4-6) pathway is common in several types of cancers, including GBM; a phase II trial evaluated palbociclib, an oral inhibitor of CDK4–6, in rGBM patients with RB1 (Retinoblastoma) proficiency in IHC." (PMID 33375286, 2020). "We found that the expression of Cyclin E and CDK2 was downregulated in retinoblastoma cells with TAZ knockdown, but no obvious changes were observed in Cyclin D1, CDK4 and CDK6 expression." (PMID 26464030, 2015).
thyroid cancer (13 papers, 2009 to 2024). "Here, we interrogated, for the first time, the presence of T172-phosphorylated CDK4 in the different sub-types of thyroid cancer." (PMID 37964967, 2023). "CDK4 phosphorylation was detected in all well-differentiated thyroid carcinomas (n=29), 19/20 PDTC, 16/23 ATC and 18/21 thyroid cancer cell lines, including 11 ATC-derived ones." (PMID 37964967, 2023). "Similar results are observed that CDK4/6 inhibitors suppress the proliferation of thyroid cancer cells." (PMID 31358010, 2019). "Induction of apoptosis following CDK4/6 inhibition in thyroid cancer cells involved a modulation of FOXM1, cyclin A1 and myc." (PMID 30349650, 2018). "We have applied a combined therapeutic approach using, for the first time to the best of our knowledge, BRAFV600E and CDK4/6 inhibitors in human thyroid carcinoma cells." (PMID 29156680, 2017). "The aims of this work were to define if the CDK4 phosphorylation can be detected in thyroid cancer, whether it is variable and indicative of sensitivity to CDK4/6i and predictable on a biomarker based upon protein and/or mRNA expression." (PMID 37964967, 2023). "To summarize, the upregulation of Cyclins D with stabilization of activated (T172-phosphorylated) CDK4 complexes and the upregulation of Cyclin E1 with increase of its kinase activity are most probably the mechanisms that bypass CDK4/6 inhibition in thyroid cancer cells." (PMID 37964967, 2023). "Thus, inhibition of ERK pathway synergizes with CDK4/6i, potentiating the proliferation-suppressive properties of each of the drugs and strongly impairing the long-term growth of thyroid cancer cells and the development of resistance." (PMID 37964967, 2023). "Furthermore, we aimed to identify drug combinations including CDK4/6i, which actively block the growth of advanced thyroid cancers, providing the rationale for testing in clinical trials." (PMID 37964967, 2023). "Several molecular evidence suggest that CDK4/6i could be considered for treating these advanced thyroid cancers." (PMID 37964967, 2023). "However, no CDK4 mutation has been identified in any types of thyroid cancer so far according to the public resource, consistent with the rarity of cPTC-related brain metastasis." (PMID 34249677, 2021). "Although further studies will be necessary, our results suggest that targeting BRAFV600E and CDK4/6 in aggressive thyroid cancer can trigger apoptosis by overcoming CDK4/6-dependent cell cycle checkpoints dysfunctions which could allow or even lead to genomic instability." (PMID 29156680, 2017).
chondrosarcoma (12 papers, 2014 to 2026). A malignant cartilaginous matrix-producing mesenchymal neoplasm arising from the bone and soft tissue. "In chondrosarcoma, previous studies reported that expression of CDK4 was associated with high-grade chondrosarcoma in both patients’ samples and cell lines, which suggests an important role in the pathogenesis and treatment of chondrosarcoma." (PMID 30808351, 2019). "More importantly, CDK4 expression levels were also associated with the metastasis and recurrence stage of chondrosarcoma." (PMID 30808351, 2019). "CDK4 is highly expressed in chondrosarcomas and associated with poor prognosis." (PMID 39590345, 2024). "Similarly, CDK4, linked to cell cycle regulation and associated with a poor prognosis in chondrosarcoma, can be targeted by palbociclib or CDK4-specific siRNA, which significantly reduces tumor cell proliferation and spread via cell cycle arrest." (PMID 39590345, 2024). "Additionally, CDK4, a protein linked to cell cycle regulation, is highly expressed in chondrosarcomas and associated with metastasis and poor prognosis." (PMID 39590345, 2024). "Targeting CDK4 with palbociclib or CDK4-specific siRNA has demonstrated substantial reductions in chondrosarcoma cell proliferation, migration, and invasion by inducing cell cycle arrest in the G1 phase, mainly through the CDK4/Rb signaling axis." (PMID 39590345, 2024). "An illustration of the consequences of this for individual patients is a case of chondrosarcoma where CDK4 gene amplification was identified by RNA sequencing and a CDK4/6 inhibitor was commenced according to the recommendation of a molecular tumor board." (PMID 37197427, 2023). "Palbociclib, an inhibitor of CDK4, induced cell cycle arrest in the G1 phase and inhibited the proliferation, migration, and invasion of chondrosarcoma cells through the CDK4/Rb signaling pathway." (PMID 35163019, 2022). "As cell migration and invasion are pivotal steps in cancer cell metastasis and we observed the inhibitory effect of palbociclib on CDK4/Rb signaling in chondrosarcoma." (PMID 30808351, 2019). "Results obtained indicated that chondrosarcoma cells were inhibited in G1 stage following CDK4 abrogation and CDK4 inhibition contributed to the significant cell apoptosis effectively." (PMID 30808351, 2019). "Further study on the relationship between the clinicopathological characteristics of chondrosarcoma and CDK4 expression indicated the potent correlation between CDK4 expressions and the therapeutic prognosis of chondrosarcoma patients clinically." (PMID 30808351, 2019). "We used immunohistochemistric analysis to evaluate human CDK4 productions in chondrosarcoma tissues." (PMID 30808351, 2019). "The vivid crosstalk that related the expression of CDK4 to the malignant features plus treatment effects of chondrosarcoma patients, was also evaluated." (PMID 30808351, 2019). "Firstly, we used specific CDK4 siRNA to down-regulate chondrosarcoma CDK4 level for cell viability evaluation." (PMID 30808351, 2019). "The attenuation of CDK4 inhibits chondrosarcoma cell viability via downregulation of the CDK4/Rb signaling pathway." (PMID 30808351, 2019). "To explore the vital roles of CDK4 in chondrosarcoma, we determined the expression of CDK4 in human chondrosarcoma tissues." (PMID 30808351, 2019). "In order to evaluate the potential regulatory molecular action of mechanisms that inhibiting chondrosarcoma cell survival and proliferation after CDK4 targeting treatment, the effect of palbociclib on progress of the cell cycle and apoptosis was examined." (PMID 30808351, 2019). "Further, the effect of palbociclib-mediated inhibition of CDK4 expression on the migration and invasion activity of chondrosarcoma was assessed." (PMID 30808351, 2019).